MAOB (monoamine oxidase B)
Diseases named in the same sentence as MAOB in open-access papers (continued):
Sharing a sentence is not in itself a finding about the gene and the disease.
atherosclerosis (1 paper, 2023). A disease characterized by the build-up of fatty material and calcium deposition in the arterial wall resulting in partial or complete occlusion of the arterial lumen. "Due to the crucial role of MAOB activation in the progression of endothelial oxidative stress and dysfunction, it is worthwhile investigating whether MAOB inhibitors can exert beneficial therapeutic effects on atherosclerosis." (PMID 37299505, 2023). "However, whether MAOB regulates endothelial oxidative stress and its related mechanism and whether gut microbiota mediates the anti-atherosclerosis effect of MAOB inhibitor remains unclear." (PMID 37299505, 2023). "However, the previous studies have not focused on the exact mechanism by which MAOB regulates endothelial oxidative stress and the upstream regulator of elevated MAOB, and explored whether gut microbiota mediates the therapeutic effects of selegiline on atherosclerosis." (PMID 37299505, 2023).
bipolar depression (1 paper, 2025). "While HTR1A, HTR2A, and HTR7 are known targets of lurasidone, MAOB, HTR3A, SLC18A2, and HTR1B were identified for the first time as targets of lurasidone potentially involved in its associated induction of acute manic episodes in people with bipolar depression." (PMID 40202273, 2025). "Our bioinformatics and computational analyses demonstrated that lurasidone may regulate the serotonergic synapse signaling pathway by targeting proteins such as MAOB, HTR1A, HTR2A, HTR3A, SLC18A2, HTR1B, and HTR7 to induce treatment‐emergent mania in people with bipolar depression." (PMID 40202273, 2025). "This study revealed that lurasidone may regulate the serotonergic synapse signaling pathway by interacting with the identified core targets MAOB, HTR1A, HTR2A, HTR3A, SLC18A2, HTR1B, and HTR7 to induce treatment‐emergent mania in people with bipolar depression." (PMID 40202273, 2025).
brain injury (1 paper, 2023). Acute and chronic (see also brain INJURIES, CHRONIC) injuries to the brain, including the cerebral hemispheres, CEREBELLUM, and brain STEM. "Notably, bumetanide and VEGF inhibitors show promise for traumatic brain injury (TBI), while monoamine oxidase B (MAO-B) inhibitors and A2A receptor antagonists hold potential for AD." (PMID 37720543, 2023).
breast tumor (1 paper, 2025). "Then, in contrast to normal breast tissue, breast tumor tissue had considerably lower MAOB expression levels and higher levels of CYCS, XBP1, HSPA4, APEX1, and SERP1." (PMID 41367017, 2025).
cerebral infarction (1 paper, 2025). An ischemic condition of the brain, producing a persistent focal neurological deficit in the area of distribution of the cerebral arteries. "Another tracer, 18F-THK5351, binds to monoamine oxidase-B (MAO-B), facilitating the identification of astrogliosis in various neurodegenerative diseases and in cases of cerebral infarction." (PMID 41362305, 2025).
chronic atrophic gastritis (1 paper, 2025). Atrophic gastritis that is persistent and long-standing. "SGD alleviates Helicobacter pylori-induced chronic atrophic gastritis (CAG) by inhibiting MAOB, and Helicobacter pylori plays an important role in CAG." (PMID 41190029, 2025).
colitis (1 paper, 2024). Inflammation of the colon. "While primarily studied in neurobiology, MAOB may play a role in inflammation and oxidative stress in the gut, influencing the pathophysiology of colitis." (PMID 39479684, 2024).
developmental delay (1 paper, 2022). "Studies had reported that the deletion of MAOB in a male patient caused severe developmental delay." (PMID 35268218, 2022).
gastric cancer (1 paper, 2021). A primary or metastatic malignant neoplasm involving the stomach. "Both MAOA and MAOB showed low expression in gastric cancer tissue compared with that in normal tissue." (PMID 33855088, 2021). "The norepinephrine-degrading enzymes MAOA and MAOB have significant expression differences in cancer and normal tissue, and their missing or low expression may predict immune therapy outcomes for gastric cancer patients." (PMID 33855088, 2021). "The norepinephrine levels were markedly high in gastric cancer tissue, while the norepinephrine-degrading enzymes MAOA and MAOB showed low expression." (PMID 33855088, 2021). "Given that PET-CT of gastric cancer patients could represent glycolysis activity in patients, we evaluated MAOA and MAOB expression using patient PET-CT graphics." (PMID 33855088, 2021). "Subsequently, NE synthetase enzymes tyrosine hydroxylase (TH), dopa decarboxylase (DDC), and dopamine-β-hydroxylase (DBH), degrading enzymes monoamine oxidase A and B (MAOA and MAOB), and catechol-O-methyl transferase (COMT) were analyzed in TCGA database of gastric cancer." (PMID 33855088, 2021).
glaucoma (1 paper, 2024). Increased pressure in the eyeball due to obstruction of the outflow of aqueous humor. "Finally, a series of enzymes, such as lactate dehydrogenase A or monoamine oxidase B, were also identified as predicted new targets for the management of glaucoma." (PMID 39458974, 2024).
hypogonadic (1 paper, 2020). "This haplotype is the only one that contains the MAOB rs3027452‐A allele, which is the polymorphism we have found to be overrepresented among our hypogonadic HT patients." (PMID 31743621, 2020). "Thus, the aim of this work was to study the distribution of MAOA and MAOB polymorphisms in a group of nondiabetic obese patients with and without hypogonadism to discern the possible relationship between this genetic factor with the blood pressure in hypogonadism." (PMID 31743621, 2020).
ovarian carcinoma (1 paper, 2020). A malignant neoplasm originating from the surface ovarian epithelium. "Only high expression of UBE2C, TK1, TACC3 and CXCR4 and low expression of MAOB were proved to be associated with poor prognosis of patients with ovarian cancer, suggesting the five genes were considered to be the key genes in ovarian cancer." (PMID 33123295, 2020).
rectal adenocarcinoma (1 paper, 2025). "The signature comprises three macrophage-related genes—TIMP1, MAOB, and PYGM—that robustly stratify rectal adenocarcinoma (READ) patients by prognosis." (PMID 40873584, 2025).
vitiligo (1 paper, 2019). Generalized well circumscribed patches of leukoderma that are generally distributed over symmetric body locations and is due to autoimmune destruction of melanocytes. "In the present study, our analysis suggested that KBL might be of therapeutic effects on vitiligo by affecting catecholamine metabolism, neurotransmitter degradation (MAOA and MAOB), and intracellular steroid hormone receptor signaling pathway (ESR1)." (PMID 31781265, 2019).
withdrawal syndrome (1 paper, 2022). "To date, no DRT-related withdrawal syndrome has been described in PD patients who discontinue rasagiline, an irreversible inhibitor of monoamine oxidase-B (MAO-B)." (PMID 35203982, 2022).
neurodegenerative disease (71 papers, 2012 to 2026). A disorder of the central nervous system characterized by gradual and progressive loss of neural tissue and neurologic function. "With their acute neurotransmitter- and cathecolamine-oxidizingactivities, MAOA and MAOB are among the principal enzymatic sourcesof ROS and are implicated in various neurodegenerative diseases." (PMID 40042998, 2025). "The by-products H2O2 and ammonia during the MAOB-mediated production of GABA are key molecules causing reactive astrogliosis in neurodegenerative diseases." (PMID 39815261, 2025). "Genetic variants in the MAOB gene were linked to alterations in MAOB enzyme activity or gene expression, showing correlations with several neurodegenerative diseases." (PMID 38520217, 2024). "NTF also inhibits BACE1, Monoamine oxidase-B (MAO-B), tau hyperphosphorylation, and Aβ aggregation, thereby inhibiting neurodegenerative diseases, especially AD." (PMID 40271071, 2025). "In a first study published in 2022 they developed a small library of cinnamic acid‐inspired photoswitchable multitarget inhibitors targeting both AChE and monoamine oxidase B (MAO‐B), both implicated in neurodegenerative diseases." (PMID 40123150, 2025). "We showcased the increased oxidative stress in astrocytes via Aβ-putriscine-MAOB axis, highlighting the sensor's relevance in validating neurodegenerative disease models." (PMID 38585715, 2024). "One possible source of increased oxidative stress are elevations in brain monoamine oxidase B (MAO-B) levels, which have been demonstrated to increase with age and in association with neurodegenerative disease both in humans and in mice." (PMID 22329629, 2012). "The objective of this work was to create an effective model using derivatives of 6-hydroxybenzothiazole-2-carboxamide and establish a dependable predictive foundation for the development of neuroprotective monoamine oxidase B inhibitors for the treatment of neurodegenerative diseases." (PMID 39810525, 2025). "And we screened and identified a variety of monoamine oxidase B inhibitors from ASE that may offer therapeutic potential in neurodegenerative diseases." (PMID 36865944, 2023). "Inhibitors of monoamine oxidase A (MAO-A) and monoamine oxidase B (MAO-B) are clinically used to treat psychiatric and neurodegenerative diseases, respectively." (PMID 40076286, 2025).
tumor (53 papers, 2009 to 2026). "Our findings suggest that genetic variations and downregulation of MAOB may play potential roles in PCa development, and the MAOB rs3027452 and rs1799836 polymorphisms may serve as pivotal markers for predicting PCa tumour metastasis and prognosis." (PMID 38520217, 2024). "Additionally, high expression of MAOB in tumor stroma is associated with poor clinical outcomes in patients with PCa." (PMID 39335188, 2024). "In conclusion, we demonstrated for the first time that MAOB functions as a potential tumor suppressor, inhibiting ccRCC growth." (PMID 41338163, 2025). "After elucidating the tumor-suppressive role and related mechanisms of MAOB in ccRCC, we next searched for potential inducers of MAOB." (PMID 41338163, 2025). "A significant downregulation of MAOB levels was observed in ccRCC tissues, and this was correlated with advanced clinical stages, larger tumor sizes, and poor prognoses." (PMID 41338163, 2025). "While these findings underscore the tumor-suppressive role of GGA, they also raise an important question: how does the age-associated decline in MAOB expression establish a window of vulnerability that permits tumor initiation?" (PMID 41142201, 2025). "Consistent with our in vitro findings, IHC staining of tumor tissues showed increased MAOB expression and a reduced Ki-67 proliferation index in Caki-1/MAOB tumors compared to Caki-1/Neo-injected tumors." (PMID 41338163, 2025). "Lower MAOB transcript and protein levels were observed in RCC tissues compared to normal tissues and were associated with larger tumor sizes." (PMID 41338163, 2025). "At the end of the experiment, xenografts from the Caki-1/MAOB group had significantly lower tumor weights than those in the control group." (PMID 41338163, 2025). "Monoamine oxidases (MAOA and MAOB) are mitochondrial enzymes that degrade various monoamine neurotransmitters, which have been recognized as important regulators of tumor progression." (PMID 41338163, 2025). "In this work, we detected the mRNA and protein expression in clinical specimen and LUAD cell lines, and explored the role of MAOB in tumor proliferation and metastasis in vitro and vivo." (PMID 38434969, 2024). "In clinical observations, correlations of lower MAOB expression levels with higher Gleason scores, advanced clinical T stages, tumour metastasis, and poorer prognosis in PCa patients were noted." (PMID 38520217, 2024). "Next, we assessed connections of these four MAOB genetic variants with PCa clinicopathologic features, including iPSA levels, clinical TNM stages, pathologic T and N stages, tumour invasion statuses, D'Amico classification and BR." (PMID 38520217, 2024). "Consistent with the mRNA expression pattern, we observed that LUAD tissue expressed a lower quantity of MAOB protein using the Clinical Proteomic Tumor Analysis Consortium (CPTAC) database." (PMID 38434969, 2024). "We also identified the MAOB and MAOA genes to be under selection, where MAOB has been shown to be correlated with HiF-1α (tumour grade and hypoxia-inducible transcription factor)." (PMID 38500079, 2024). "In conclusion, these in vitro cell studies provide further validation of the tumour‐suppressive role of MAOB in PCa progression." (PMID 38520217, 2024). "Various monoamine oxidase B inhibitors have shown promise in inhibiting tumor growth and inducing apoptosis across different cancer types." (PMID 39795182, 2024). "To further explore the biologic effect of MAOB on tumor progression, we overexpressed MAOB in PC9 and A549 cell lines using lentivirus." (PMID 38434969, 2024).
tumor (continued). "We also examined the distribution of each gene in the 5-gene signature in GGO cells and discovered PLD4, NT5E and MAOB were differentially expressed between cancer cells and non-tumor cells, suggesting a more critical physiological significance." (PMID 38434969, 2024). "MAOA (T; p = 0.005) and MAOB (T; p = 0.006) in tumor cells were higher in ACN, whereas LOX was higher in tumor cells (T; p < 0.001) and LOX in stromal cells (S; p < 0.001) and AOC3 in tumor cells (T; p < 0.001) were higher in PCC." (PMID 37509535, 2023). "The H-scores of MAOA (T; p = 0.005) and MAOB (T; p = 0.006) in tumor cells (T) were high in ACN, whereas LOX (T, S; p < 0.001) in tumor and stromal cells (S) and AOC3 (T; p < 0.001) were higher in PCC." (PMID 37509535, 2023). "We found that Patient CASE 1, with a high SUVmax value and glycolysis, showed low MAOA and MAOB expression in the tumor tissue." (PMID 33855088, 2021). "Patient CASE 2, who had a low SUVmax value and glycolysis, showed high MAOA and MAOB expression in the tumor tissue." (PMID 33855088, 2021). "The MAOA or MAOB expression levels in tumor tissue were closely correlated with the patient SUV max values of PET-CT and immunotherapy evaluation indices, such as PD-L1 and the microsatellite status." (PMID 33855088, 2021). "The MAOA (p ≤ 0.001) and MAOB (p ≤ 0.001) mRNA levels were significantly higher in normal tissues than in tumor tissues." (PMID 33855088, 2021). "Our data showed that CRC patients with high MAOB expression in the primary tumor had worse OS and DFS, as well as higher recurrence rate than patients with low MAOB expression." (PMID 32316576, 2020). "Our data found MAOB expression was significantly higher in CRC tissues compared to the non-tumor counterparts." (PMID 32316576, 2020). "In particular, MAOB + NAB2 showed an AUC of 0.91 in the under–60 age group of non-tumor and cancer patients together." (PMID 31963366, 2020). "GBM157 is one of the samples on our tumor microarray and the levels of MAOB are in the lowest quartile." (PMID 29844863, 2018). "We found that MAOB levels correlated with tumor grade and hypoxia-inducible factor 1-alpha (HiF-1α) expression." (PMID 26689994, 2016). "Down-regulation was seen for CNTN1, CXCL13, MAOB, PAGE4, PENK, SPOCK3 in CP compared to NP as well as for HSD17B2, SALL1, TRPA1 for tumor-associated bladder stromal cells compared to normal bladder." (PMID 19737398, 2009). "The idea that age-dependent changes in MAOB and GGA may underlie the shift from a tumor-suppressive to a tumor-permissive hepatic microenvironment introduces a compelling paradigm for metabolic carcinogenesis." (PMID 41142201, 2025). "Collectively, these findings suggested that HNF1A may act as a co-regulator of the tumor-suppressive effects of MAOB." (PMID 41338163, 2025). "Furthermore, DepMap analyses suggested a reverse correlation between STC2 and MAOB expression in a series of human tumour cells." (PMID 38464261, 2024). "Collectively, while MAOA was reported to be an oncogene, our findings from gene correlation and expression analyses suggest that MAOB may potentially function as a tumour‐suppressive gene in PCa." (PMID 38520217, 2024). "In fact, pharmacological inhibition of stromal MAOB reduces tumor growth in vivo." (PMID 39335188, 2024). "To address whether the observation in cell culture is relevant to tumour progression in vivo, we first performed IHC staining and confirmed the elevated expression of MAOB in STC2 knockdown xenografts." (PMID 38464261, 2024). "Furthermore, we demonstrated that the tumour‐suppressive role of MAOB was dependent on its enzyme activity in PCa cells." (PMID 38520217, 2024). "The inhibition of MAOB could be a potential new strategy to counteract PCa tumor progression and ameliorate the clinical outcome of PCa patients." (PMID 39335188, 2024).